CD4 (CD4 molecule)
Diseases named in the same sentence as CD4 in open-access papers (continued):
Sharing a sentence is not in itself a finding about the gene and the disease.
bladder cancer (140 papers, 2006 to 2026). "When examining proteins overexpressed in major immune cell populations, we found that HAM/TSP IgG frequently targeted P3H4, a nucleolar protein associated with bladder cancer, across CD4+, CD8+, and γδ T cell populations." (PMID 41303346, 2025). "This correlation has been explained by the recruitment of ERβ-expressing mast cells and CD4+ T cells in bladder cancer and by the association of mast and CD4+ T cells in the tumor microenvironment with enhanced invasiveness of bladder cancer cells." (PMID 39175529, 2024). "In this study, we identified PD1hi CD200hi CD4+ exhausted T cells in bladder cancer, which are closely associated with poor prognosis and immunotherapy resistance." (PMID 37313656, 2023). "Previous research has provided evidence supporting the association between the presence of resting memory CD4+ T-cells and the prognostic outcomes of bladder cancer." (PMID 38023241, 2023). "High expression of activated memory CD4 T cells was associated with better clinical prognosis in patients with bladder cancer." (PMID 36081665, 2022). "In the GSE120736 bladder cancer cohort, B cells and CD4+ central memory T cells (CD4 + Tcm) were lower in the high-risk subgroup than in the low-risk subgroup." (PMID 34901008, 2021). "A study about bladder cancer also indicated that a high fraction of T cells CD4 memory activated was associated with better outcomes." (PMID 33442396, 2021). "Intriguingly, bona fide cytotoxic CD4+ T cells have been described in patients with bladder cancer and when present intratumorally are associated with improved responses to checkpoint inhibition." (PMID 33497362, 2021). "Li once reported that high expression of activated CD4 (+) memory T cells and low expression of M0 macrophage were associated with better clinical prognosis in bladder cancer." (PMID 34122523, 2021). "This molecule was also identified in the predictive cytotoxic CD4+ T cell-associated signature in bladder cancer." (PMID 34910940, 2021). "Single cell RNA sequencing (scRNA-seq) revealed that several states of cytotoxic CD4+ T cells are present within human bladder cancer and that a specific gene expression signature associates with response to PD-L1 Ab therapy." (PMID 33546283, 2021). "This was proven in a murine bladder cancer model where depletion of either CD4 or CD8 lymphocyte resulted in a loss in BCG-mediated antitumor activity." (PMID 31817179, 2019). "Physicians in charge of HIV-infected patients should be aware that their patients, as they become older, face an increased risk of bladder cancer, especially those with a low nadir CD4 cell count, who smoke, and also potentially those with HPV infection." (PMID 26642314, 2015). "Moreover, high infiltration of memory‐activated CD4+ T cell subsets were associated with prolonged OS and reduced risk of tumor recurrence in bladder cancer." (PMID 34374227, 2021). "Finally, two recent reports showed that a cytotoxic CD4 T-cell gene signature was associated with immunotherapy response in bladder cancer and that mismatch-repair deficient, MHC-I low tumors were highly infiltrated with CD4 T cells." (PMID 34201655, 2021). "Indeed, the presence of cytotoxic CD4+ T cells in pre-treatment tumors, based on expression of a gene signature associated with these cells, was predictive of clinical response to anti-PD-L1 in bladder cancer." (PMID 34910940, 2021). "While murine bladder carcinoma cells can present BCG antigens to BCG-specific CD4+ T cells in vitro, this remains to be demonstrated in human bladder cancer cells." (PMID 41312368, 2025). "These can be shared antigens, or MHC class II–restricted neoantigens as has been demonstrated for cytotoxic CD4+ TILs in patients with bladder cancer." (PMID 40299576, 2025). "The results showed that the expression level of AKT1 in bladder cancer was positively correlated with tumor purity, infiltration abundance of CD4 + T Cell, Macrophage, Neutrophil and Dendritic Cell." (PMID 41287122, 2025).
bladder cancer (continued). "In both untreated and immunotherapy-treated patients with bladder cancer, proliferation of circulating cytotoxic CD4+ T cells was accompanied by downregulation of KLRG1." (PMID 40299576, 2025). "The bias between either GZMK+ or GZMB+ cytotoxic CD4+ T cells has been observed in bladder cancer and CD4+CXCL13+ TFH-like cells in endometrial cancer." (PMID 41030456, 2025). "Alterations in NK cell resting and T cells CD4 memory resting populations have been observed in the tumor microenvironments of colon and bladder cancer patients." (PMID 39691602, 2024). "More recently, scRNAseq of TILs in human bladder cancer samples revealed the presence of CD4 CTLs expressing granzymes and perforin." (PMID 38968186, 2024). "T cells CD4 memory activated was positively correlated with good prognosis in breast and bladder cancer." (PMID 38742936, 2024). "Recent transcriptional analysis revealed that a cytotoxic CD4+ T cell gene signature in bladder cancer predicts a positive response to neoadjuvant anti-PD-L1 immunotherapy." (PMID 39185202, 2024). "While the mouse model cannot be directly applied to human liver or bladder cancer, the results demonstrated that there is at least an immune environment in which CD4+ T cells are a key member of the tumor elimination mechanism." (PMID 39106430, 2024). "While functional CD8+ T cells are generally correlated with antitumor responses, a recent study showed that intratumoral CD4+ T cells have tumor cytotoxic function in human bladder cancer." (PMID 38345536, 2024). "Using in vitro experiments, we further proved that PD1hi CD200hi CD4+ exhausted T cells contribute to stimulating angiogenesis in bladder cancer." (PMID 37313656, 2023). "More importantly, bladder cancer patients with high proportions of PD1hi CD200hi CD4+ exhausted T cells showed a worse response to immunotherapy than those with PD1hi CD200low CD4+ exhausted T cells." (PMID 37313656, 2023). "Similar findings were also shown in patients with bladder cancer, where clonally expanded cytotoxic CD4 T cells were enriched in the tumor vs the surrounding healthy tissue and predicted response to anti-PD1 blockade." (PMID 37654482, 2023). "The CD4, CD20 and PD-L1 expressed on tumor cells were independently associated with the risk of recurrence of bladder cancer in the Cox proportional hazard multiple regression analysis of recurrence-free survival." (PMID 38067231, 2023). "These cells showed similarities to the tumour-specific CD4+ CTLs that were found in bladder cancer patients." (PMID 37122720, 2023). "In bladder cancer, CD4+ tumor-infiltrating lymphocytes are directly cytotoxic for autologous cancer cells and CD4+ T effectors recognize antigen on cancer cells in a class II-dependent fashion." (PMID 37565053, 2023). "The TissueFAXS cytometry panoramic tissue quantification assay was further applied to reveal the spatially exclusive role of S100A5+ bladder cancer cells and CD4+ and CD8+ T cells." (PMID 37414584, 2023). "in bladder cancer highlighted the presence of distinct subsets of CD4+ T CTL in the tumor microenvironment, expressing different combinations of cytolytic genes (GZMA, GZMB, GZMK, PRF1)." (PMID 37965314, 2023). "Subsequent investigations have gathered evidence supporting the indispensable role of CD4+ CTLs in tumor immunity for other cancers, such as lung, colorectal, and bladder cancers." (PMID 38077321, 2023). "In this study, we constructed a pancancer CD4+ T‐cell atlas based on single‐cell RNA‐Seq data from patients with multiple cancers types and identified two clusters of PD1hi CD200low and PD1hi CD200hi CD4+ exhausted T cells in bladder cancer patients." (PMID 37313656, 2023). "This study described a significant increase in the frequency of both CD3+ and CD4+ cells in peripheral blood of chronic S. haematobium-infected patients who developed bladder cancer, demonstrating a possible correlation." (PMID 37068081, 2023).
bladder cancer (continued). "In bladder cancer, a cytotoxic CD4 T cell gene signature strongly predicts response to atezolizumab (anti-PDL1)." (PMID 37654482, 2023). "Our results demonstrated the CD4+ T cells play an essential role in combination OXP and anti-PD-1 therapy, which will further improve the understanding of CD4+ T cells population in bladder cancer." (PMID 36960067, 2023). "These two observations suggest that direct killing of tumor cells by cytotoxic CD4 T cells was important for the efficacy of anti-PDL1 in bladder cancer." (PMID 37654482, 2023). "The cytotoxic CD4 T cells from the bladder cancer patients directly killed matched tumor blasts in an MHCII-dependent manner." (PMID 37654482, 2023). "The clinical significance of key CD4+ T‐cell clusters was evaluated based on the survival data of two independent immunotherapy bladder cancer (BLCA) cohorts." (PMID 37313656, 2023). "Single-cell transcriptomic analyses in bladder cancer patients have recently identified multiple states of intratumoral CD4 CTLs." (PMID 35572552, 2022). "COL4A2 expression is positively correlated with the presence of macrophage and dendritic cell infiltration in cervical-cell cancer, while COL1A1 is positively correlated with tumor infiltration levels of macrophages and CD4+ T cells in bladder cancer." (PMID 33790966, 2021). "Increased expression of activated CD4+ memory T cells had been confirmed to be beneficial for prognosis in bladder cancer, and the previous study of our team also provided evidence for the opinion." (PMID 34901000, 2021). "Previous study shown that COL1A1 was correlated positively with the tumor infiltration levels of CD4+ T cells and macrophages in Bladder Cancer." (PMID 33850663, 2021). "Together with the predictive value of a cytotoxic CD4+ T cell signature for anti-PD-L1 response in bladder cancer, this suggests a role for PD-1 blockade in enhancing the activity of these cells." (PMID 34910940, 2021). "scRNA-seq of tumor-infiltrating lymphocytes (TIL) reveals discrete states of cytotoxic CD4+ T cells expressing cytolytic proteins in human bladder cancer." (PMID 34910940, 2021). "Moreover, previous studies reveal that activated memory CD4 T cells have the least proportion in clinical stage IV of bladder cancer and are associated with beneficial prognosis, which may directly kill tumors or activate the body’s immune response to destroy the tumor cells." (PMID 34136488, 2021). "It is reported that resting memory CD4+ T cells are often related to prognosis of malignant tumor diseases, such as head and neck squamous cell carcinoma and bladder cancer." (PMID 34745095, 2021). "To clarify the role of CD4+ regulatory T cells in bladder cancer, we investigated the frequency of these cells in tumor draining lymph nodes of 50 patients with bladder cancer who underwent radical cystectomy using flow cytometry method." (PMID 33305045, 2020). "Previous research found that CD3D/CD4 ratio is an important marker for the prognosis of bladder cancer." (PMID 33204728, 2020). "On average, 30.13 ± 2.17% of lymphocytes in draining lymph nodes from patients with bladder cancer were positive for both CD4 and FOXP3 molecules." (PMID 33305045, 2020). "Intriguingly, a role in Th2 polarization has been suggested for the little known double positive CD4+veCD8+ve T cell population which was found to be expanded in the blood of patients with bladder cancer in a recent study." (PMID 31824850, 2019). "In particular, our results showed that neoantigen loads had an association with the relative abundances of both T cell CD8+ and CD4+ memory-activated, and B cell naïve and memory types in bladder cancer." (PMID 31533728, 2019). "rBCG-S1+S1i was able to express the two forms of S1PT and elicited higher induction of polyfunctional CD4+ T cells, indicating enhanced immunogenicity and suggesting its use as immunotherapy for bladder cancer." (PMID 30941374, 2019).
bladder cancer (continued). "A recent study of methylation patterns of CD4 T cells from the tumor in patients with bladder cancer showed that a higher stage was correlated with increased methylation (and thus reduced expression) at the IFN-γ locus." (PMID 31824850, 2019). "Altogether, these findings indicate that the encapsulation of BCG-CWS into the functionalized liposomes is beneficial for intracellular translocation of the cargo into bladder cancer cells, ultimately mediating the antitumor effect with IL-6 and CD4." (PMID 31817179, 2019). "Whilst suggestive of an adverse correlation with Th2 skewing, the evidence above is inconclusive for the role of Th1 and Th2 helper CD4 cells in bladder cancer." (PMID 31824850, 2019). "BCG-mediated protection against TB and bladder cancer has been shown to rely on its ability to induce superior CD4+ and CD8+ T cell responses." (PMID 29848490, 2018). "In the present study, we evaluated tumor-infiltrating lymphocytes (TILs) and blood regulatory T lymphocyte (Tregs, CD4+/CD25+/FoxP3+) expression in bladder cancer patients." (PMID 26927070, 2016). "A decreased frequency of CD4+CD25hiCD127lo Treg was present in the apparently free-of-tumor bladder tissue with respect to the autologous bladder cancer." (PMID 26824503, 2016). "At the time of bladder cancer, median CD4 cell count was 506 cells/mm3, and most patients were receiving antiretroviral therapy (86%), and had suppressed viral replication in plasma (64%)." (PMID 26642314, 2015). "In support of this view, bladder cancer patients receiving anti-CTLA4 therapy showed an increase in the ratio of effector to regulatory T cells as well as tumor antigen-specific CD4 T cells." (PMID 22013484, 2011). "In bladder cancer, lentinan is an isolated botanical drug metabolite that induces macrophage activation in a bladder cancer mouse model, promoting the proliferation of CD4+ and CD8+ T cells while upregulating the expression of IFN-γ and IL-2." (PMID 41458964, 2025). "Previous studies have shown that cytotoxic CD4+ T cells and NK cells could mediate the antitumor responses of bladder cancer." (PMID 39964752, 2025). "Cytotoxic CD4+ circulate between the blood and tumor of bladder cancer patients, where they exist as clonally related but distinct pools of granzyme B+ effector cells dually inhibited by PD-1 and KLRG1, and effector memory granzyme K+ cells that are not mobilized by PD-1 blockade." (PMID 40299576, 2025). "Similarly, the CD4+ T cells being capable of killing autologous human bladder cancer cells, are subject to inhibition by Tregs." (PMID 41030456, 2025). "Human urothelial cancers upregulate expression of HLA-DR, suggesting that cytolytic CD4+ T cells may be more important for antitumor responses in bladder cancer." (PMID 38345536, 2024). "We found that in bladder cancer, the expression of CD4 T cells, CD8 T cells, cDCs, epithelial cells, macrophages, mast cells, and plasma cells showed an up-regulated trend, while the expression of B cells, fibroblasts, and monocytes showed a down-regulated trend." (PMID 39120585, 2024). "Similarly, a group of efficiently responsive CD4+ICOS+ (inducible co‐stimulator) T cells is identified as a phenotype of Th1 cells in bladder cancer patients who are all treated with Ipilimumab (anti‐CTLA‐4)." (PMID 37829505, 2023). "We conclude that an immunotherapy/anti‐CD200 combination might offer a promising therapeutic option for bladder cancer patients with high proportions of PD1hi CD200hi CD4+ exhausted T cells." (PMID 37313656, 2023). "However, another study of bladder cancer demonstrated that the m6A score was positively correlated with CD4 T immune cell, CD8 T immune cell, and dendritic immune cell number, while negatively correlated with PD-L1 expression level." (PMID 37701836, 2023). "In addition, we also found that bladder cancer cells can recruit PD1hi CD200hi CD4+ exhausted T cells to promote EMT by enhancing m6A‐mediated GAS6." (PMID 37313656, 2023).
bladder cancer (continued). "In addition, regulatory and cytotoxic CD4 T cells have been found to be enriched and clonally amplified in various cancers, including bladder cancer." (PMID 37994323, 2023). "Finally, we observed that malignant cells can recruit PD1hi CD200hi CD4+ exhausted T cells to induce EMT in bladder cancer cells by releasing m6A‐mediated GAS6." (PMID 37313656, 2023). "Similarly, intratumoral cytotoxic CD4+ T cells have been shown to mediate MHC class II-dependent killing of human bladder cancer cells." (PMID 37161048, 2023). "Besides, CD4 + T cells play an anti-tumor role in human bladder cancer, and the higher levels of CD4 + T cells infiltration had a better prognosis than the lower levels in sarcoma patients." (PMID 36627705, 2023). "In addition, PD1hi CD200low CD4 and PD1hi CD200hi CD4 exhausted T‐cell subsets were also isolated from the blood of 18 bladder cancer patients, 10 non‐small cell lung carcinoma patients and 8 esophageal squamous cell carcinoma patients by magnetic sorting." (PMID 37313656, 2023). "Furthermore, a recent publication showed similar cytotoxicity for CD4 tumor-infiltrating-lymphocytes (TILs) in bladder cancer." (PMID 36439452, 2022). "In contrast to a recent study where CD4 T cells with cytotoxic activity were found infiltrating human bladder cancers, we have previously shown that Marilyn CD4 T cells lack cytotoxic activity and that their antitumor effect does not rely on direct antigen recognition on tumor cells." (PMID 35903540, 2022). "To test the role of antitumor CD4 T effector cells as part of a natural endogenous response, we depleted female C57Bl/6 (B6) mice of their CD4 or CD8 T cells 5 days before challenging them with the bladder carcinoma MB49 cell line, which spontaneously expresses the H-Y male antigen." (PMID 35903540, 2022). "Besides, a study has shown that in bladder cancer, CD4 memory activated T cells are related to the good prognosis of patients." (PMID 34304692, 2021). "Additionally, a recent bladder cancer study showed that the tumor-specific gene expression program of cytotoxic GZMB+ CD4+ T cells treated with anti-PD-L1 therapy was marked by tumor overexpression of CXCL1353." (PMID 34795254, 2021). "Interestingly, a statistically significant increase in CD4+CD25hiCD127lo Treg frequency was observed among circulating lymphocytes from bladder cancer patients as compared to renal cancer patients." (PMID 26824503, 2016). "Instead, the frequency of CD4+ Treg was lower in renal cancer compared to bladder cancer indicating that the level of tumor infiltration by Treg may have pathogenic relevance." (PMID 26824503, 2016). "Interestingly, a significantly increased frequency of CD4+CD25hiCD127lo Treg was detected among TIL purified from bladder cancer samples as compared to those extracted from renal cancer samples." (PMID 26824503, 2016). "This single patient had a diagnosis of bladder cancer made several months before the diagnosis of HIV but at the time HIV-infection was identified, he presented with a very low CD4 cell count suggesting that he had been infected before the diagnosis of bladder cancer." (PMID 26642314, 2015). "Bladder cancers in HIV-infected patients remain rare but may occur in relatively young patients with a low nadir CD4 cell count, have aggressive pathological features and can be fatal." (PMID 26642314, 2015). "Bladder cancers in HIV-infected patients remain rare but occur in relatively young HIV-infected patients with a low CD4 nadir, presenting with haematuria, most of them being smokers, and have aggressive pathological features that are associated with severe outcomes." (PMID 25394151, 2014). "And in yet another clinical trial in which bladder cancer patients were treated with ipilimumab, it was found that treatment-induced no consistent changes in Treg frequencies (CD4+Foxp3+, CD4+Foxp3+ICOShi, or CD4+Foxp3+ICOSlo T cells)." (PMID 23653893, 2013).